NCOA4 (nuclear receptor coactivator 4)
Diseases named in the same sentence as NCOA4 in open-access papers (continued):
Sharing a sentence is not in itself a finding about the gene and the disease.
lung carcinoma (12 papers, 2014 to 2025). "DTX2, an E3 ubiquitin ligase, exhibits significantly elevated expression in non-small-cell lung cancer (NSCLC) and regulates lung cancer cell proliferation through the ferritinophagy and ferroptosis pathways mediated by NCOA4." (PMID 40647501, 2025). "Mechanistically, Huaier simultaneously and independently downregulates the antioxidant pathway SLC7A11/GPX4 and elevates intracellular iron levels through NCOA4-mediated ferritinophagy degradation of FTH1 in lung cancer cells." (PMID 40623982, 2025). "On the other hand, while the frequency of NCOA4-RET was low (2.3%, 6/262) in lung cancer, it was the most frequent RET fusion (44%, 7/16) in colorectal cancer (Bonferroni’s post-test, P < 0.0001)." (PMID 36369474, 2022). "In a previous report, we detected 15 RET fusion transcripts in cells taken from a lung cancer patient and confirmed five RET fusion partners (KIF5B, CCDC6, TRIM33, NCOA4, and CUX1)." (PMID 27150058, 2016). "Additionally, other ferroptosis-related molecules, such as NCOA4 (nuclear receptor coactivator 4) and TXNIP (thioredoxin-interacting protein), also play important roles in ferroptosis in lung cancer." (PMID 39917300, 2025). "Upon further investigation, we found that Huaier treatment resulted in a significant increase in NCOA4 protein levels and a decrease in FTH1 protein levels in the three distinct lung cancer cell lines consistently, but did not alter the transcription level of these genes in these cell lines." (PMID 40623982, 2025).
colon cancer (10 papers, 2017 to 2025). "Selective pharmacological inhibition of VPS34 in DLD1 cells (a human colon cancer cell line) decreased NCOA4-mediated ferritin degradation, indicating NCOA4-dependent ferroptosis is regulated by VPS34." (PMID 39821606, 2025). "NCOA4 is used to be considered as a promoter of ferroptosis, yet in a recent study, it was stated that NCOA4 disruption is irrelevant to ferroptosis in colon cancer cells." (PMID 35884370, 2022). "Emodin inhibits proliferation and induces ferroptosis in colon cancer (HT-29, RKO, HCT-15 and SW620) cells by inactivating the NF-κB pathway and nuclear receptor coactivator 4 (NCOA4)-mediated ferritinophagy." (PMID 40490812, 2025). "Sinomenine is an active alkaloid from Sinomenium acutum, and its derivative facilitates interactions between nuclear receptor coactivator 4 (NCOA4) and FTH1, accelerating Fe2+ release and ultimately promoting ferroptosis in colon cancer cells." (PMID 39584140, 2024). "However, it was found to cause only minor differences in ferroptosis if NCOA4 was knocked out in colon cancer cells, indicating that ferritinophagy may not be a critical factor in the process of ferroptosis in colon cancer cells." (PMID 36005616, 2022). "Recent studies reported that NCOA4-RET was detected in 1/936 NSCLCs, 1/3117 colon cancers, and 2/149 salivary gland cancers." (PMID 29088743, 2017). "For example, the silencing of NCOA4 in colon cancer cells did not yield any noteworthy disparity in the expression of ferritin and TFR1, thereby suggesting that the growth of colon cancer cells does not necessitate the participation of ferritinophagy." (PMID 38110359, 2023).
liver cancer (9 papers, 2022 to 2026). An epithelial or non-epithelial malignant neoplasm that arises from the liver. "To demonstrate the “on-target” effect of HYP in an in vivo setting, we conducted additional assays to examine the impact of HYP on ferroptosis-related indicators (MDA and Fe2+) and NCOA4 protein levels in hydrodynamic-induced liver cancer tissues." (PMID 40514377, 2025). "Polyphyllin B, also known as Formosanin C. Moreover, Formosanin C has chemotherapeutic potential against apoptosis-resistant HCC with a higher NCOA4 expression via ferritinophagy in liver cancer cells." (PMID 38459479, 2024). "In contrast, in liver cancer cells under sorafenib treatment, PTBP1 promotes the translation of NCOA4 mRNA, a key regulator of ferritinophagy, which sensitizes cells to ferroptosis." (PMID 41313521, 2025). "In liver cancer, PTBP1 modulates ferroptosis through a mechanism involving nuclear receptor coactivator 4 (NCOA4)." (PMID 41313521, 2025). "-Inhibits the proliferation of liver cancer HUH7 and HCCLM3 cells by activating ferritinophagy in cancer cells and modulating the NCOA4/FTH1/LC3II signaling pathway for increase ferroptosis." (PMID 38397559, 2024). "The varied expression levels of DEFRGs between the tumor and control groups in the TCGA-LIHC liver cancer dataset were compared, where ZFP36, NCOA4, FTH1, FTL, TNF, and PCBP1 were matched with the TCGA transcriptome data." (PMID 37555866, 2023). "According to our experimental results, caryophyllene oxide can induce ferritinophagy in tumor cells by regulating the NCOA4/FTH1/LC3II signaling pathway, which leads to ferroptosis and the inhibition of the growth of the liver cancer cells, HCCLM3 and HUH7." (PMID 35899120, 2022). "Several studies have shown that HSPA8 inhibits ferroptosis by promoting SLC7A11/GSH/GPX4 signalling and inhibiting NCOA4-mediated ferritinophagy, We verified the effects of HSPA8 in liver cancer and found that LACTB promotes ferroptosis by regulating HSPA8-mediated ferroptosis-related signalling." (PMID 39047638, 2024).
anemia (8 papers, 2018 to 2025). A reduction in the number of red blood cells, the amount of hemoglobin, and/or the volume of packed red blood cells. "Finally, these data support study of NCOA4 in the context of multiple pathological conditions with imbalances in iron homeostasis like hemochromatosis or iron deficiency anemia." (PMID 30360520, 2018). "Mice with erythroid-specific ablation showed severe anemia postnatally but hypochromic microcytic anemia in adulthood, indicating that NCOA4 is required for erythroid differentiation in postnatal mice rather than in adult mice." (PMID 38961066, 2024). "Combining our findings and others’ previous findings, we have highlighted that Hif2α-Ncoa4 is a complex axis that contributes to iron metabolic disorders, including neurodegeneration, iron-overload disorder, and anemia." (PMID 36978814, 2023). "These identify macrophage NCOA4 as a potential therapeutic target for disorders of systemic iron dysregulation, including anemia of inflammation and hemochromatosis." (PMID 36290647, 2022). "The role of TRβ and of its coactivator NCOA4 in stimulating terminal differentiation has been shown in primary cells and in anemia mouse models, following the administration of TRβ agonists." (PMID 35269942, 2022). "NCOA4 KO mice developed a mild hypochromic microcytic anemia together with ferritin and iron accumulation in tissues, indicating inefficient iron mobilization from ferritin." (PMID 30360520, 2018). "NCOA4 appears to be more important at various stages of development as NCOA4 KO mice examined at the immediate postnatal period showed a more severe anemia." (PMID 30360520, 2018). "Systemic NCOA4 knockout mice developed more severe anemia that disrupted general iron homeostasis, resulting in the accumulation of tissue ferritin and iron, a reduction in serum iron content, and anemia." (PMID 38961066, 2024). "For example, while NCOA4 is fundamental for iron supply during erythropoiesis, when iron is abundant, such as in MDS, other compensatory mechanisms are activated to prevent anemia, providing a rationale for targeting NCOA4 suppression to reverse ineffective erythropoiesis." (PMID 38153418, 2023). "Thus, targeting the coordination of NCOA4 and TR shows potential for treating certain anemias." (PMID 38961066, 2024). "Interestingly, the NCOA4 knock-out results in transient anemia during embryonic development but this phenotype must take into account the role of NCOA4 in regulating iron metabolism that could, in turn, contribute to regulate red cells production." (PMID 35269942, 2022). "As the observed anemia is less severe in adult NCOA4 KO mice compared to young mice, this could suggest cell-autonomous or non-autonomous mechanisms that compensate for NCOA4 loss over time." (PMID 30360520, 2018).
periodontitis (8 papers, 2020 to 2025). An acute or chronic inflammatory process that affects the tissues that surround and support the teeth. "Furthermore, this study initially verified that blocking JNK/ JUN/NCOA4 axis can effectively suppress macrophages ferroptosis, resulting in a decrease in the inflammatory status associated with chronic apical periodontitis." (PMID 39744165, 2025). "These lines of evidence provide a new mechanistic insight into the mechanism of loss of PDLFs during periodontitis development, showing that periodontitis-level butyrate disrupted iron homeostasis by activation of NCOA4-mediated ferritinophagy, leading to ferroptosis in PDLFs." (PMID 33298848, 2020). "Through the establishment of the in vitro and in vivo models, we have discovered that there is a direct correlation between the JNK/JUN/NCOA4 axis and the presence of macrophage ferroptosis during chronic apical periodontitis progression." (PMID 39744165, 2025). "Remarkably, our findings from both in vitro and in vivo experiments uncovered a novel role of the JNK/JUN/ NCOA4 axis in regulating macrophage ferroptosis in chronic apical periodontitis." (PMID 39744165, 2025). "For example, P38 increases Ncoa4 transcription, leading to intracellular iron overload and ROS elevation in periodontitis." (PMID 38523594, 2024). "Butyrate disrupted iron homeostasis by activating NCOA4-mediated ferritinophagy, leading to ferroptosis in periodontitis." (PMID 35611986, 2022). "We also found that the analysis results of the downregulated genes include NCOA4, which is important in periodontitis." (PMID 35901060, 2022). "A recent study including molecular biology experiments showed that NCOA4, one of the FRGs, is related to the occurrence and development of periodontitis, indicating that iron homeostasis plays an important role in the pathogenesis of periodontitis." (PMID 35901060, 2022). "In addition, butyrate disrupted iron homeostasis by activation of NCOA4-mediated ferritinophagy, leading to ferroptosis in periodontitis." (PMID 37589000, 2023). "Furthermore, NCOA4 is considered one of ferroptosis-related genes (FRGs) contributing to butyrate-induced cell death in the periodontitis." (PMID 35901060, 2022). "Additionally, periodontitis-level butyrate could lead to ferroptosis in periodontal ligament fibroblasts via activating NCOA4-mediated ferritinophagy and destroying the iron homeostasis, leading to further development of periodontitis." (PMID 37710216, 2023). "In deep periodontal pockets, high butyrate levels promote ferroptosis in periodontal ligament fibroblasts via nuclear receptor coactivator 4 (NCOA4), worsening periodontitis." (PMID 40541947, 2025). "The expression levels of NCOA4, SLC1A5 and HSPB1 using PCR were significantly different between normal gingival samples and periodontitis samples." (PMID 35901060, 2022). "Moreover, the expression of ferroptosis-related genes, including NCOA4, SLC1A5, HSPB1, etc. were significantly upregulated in the human periodontitis-gingival samples compared to the periodontal healthy normal gingival samples." (PMID 37710216, 2023).
clear cell renal carcinoma (7 papers, 2021 to 2026). A malignant epithelial neoplasm of the kidney characterized by the presence of lipid-containing clear cells within a vascular network. "Low NCOA4 expression was associated with poor overall survival in individuals with malignancies such as cholangiocarcinoma, colon adenocarcinoma, and clear cell renal carcinoma." (PMID 35756082, 2022). "It was reported that NCOA4 depletion weakened ferroptosis, leading to unfavorable outcomes and defective immune cell infiltration in clear cell renal carcinoma." (PMID 41541703, 2026). "The expression of NCOA4 is lower in Clear cell renal cell carcinoma (ccRCC) tissues compared with normal tissues, and low NCOA4 expression is closely related to high-grade malignant tumors and advanced TNM staging." (PMID 34858857, 2021). "NCOA4 expression in clear cell renal carcinoma (ccRCC) tissues and normal adjacent tissues in The Cancer Genome Atlas (TCGA) data were primarily screened, and further validated in another independent cohort from the gene expression omnibus (GEO) database and human protein atlas." (PMID 33402128, 2021). "It has been found that low expression of NCOA4, a ferritinophagy-related gene, correlates with decreased immune cell infiltration and impaired IFN-γ receptor signaling in clear cell renal carcinoma (ccRCC)." (PMID 35756082, 2022).
colorectal cancer (7 papers, 2012 to 2025). A primary or metastatic malignant neoplasm that affects the colon or rectum. "In colorectal cancer, studies suggest that NcoA4 may contribute to carcinogenesis associated with loss of epigenetic regulation resulting from impaired histone deacetylase 2 (HDAC2) function and to metastatic progression." (PMID 22562579, 2012). "Using a genomics guided outlier approach, we identified 4 RET fusion PDX models with 3 different fusion partners (KIF5B, CCDC6, and NCOA4) in both non-small cell lung cancer and colorectal cancer." (PMID 30038711, 2018). "Increased NcoA4 expression was also detected in SW620 relative to SW480 colorectal cancer cells." (PMID 22562579, 2012). "Moreover, the colorectal cancer cells' ferroptosis could be effectively reduced by suppressing NCOA4 through the inhibition of the JNK signaling pathway with SP60012546." (PMID 39744165, 2025). "On the other hand, Le Rolle and co-workers have recently reported on the identification and characterization of RET fusions that juxtapose the C-terminal RET kinase domain to the N-terminal domain of CCD6 or NCOA4 (CCDC6-RET and NCOA4-RET fusions) in advanced colorectal cancer." (PMID 29665843, 2018). "Whereas the NCOA4-RET fusion oncogene (TII, PII) found in 1 colorectal cancer patient has been described in this tumor type, it is not usually tested." (PMID 33947144, 2021).
non-small cell lung carcinoma (7 papers, 2018 to 2025). A group of at least three distinct histological types of lung cancer, including non-small cell squamous cell carcinoma, adenocarcinoma, and large cell carcinoma. "CCDC6-RET and NCOA4-RET have been previously characterized as oncogenic and occur recurrently in papillary thyroid and non-small cell lung cancers." (PMID 34650924, 2021). "Somatic RET rearrangements (as fusion genes with CCDC6, NCOA4, KIF5B, PRKAR1A, TRIM33 and other rarer partners) have now been found in 1–2% of non-small-cell lung cancers (NSCLC) and at lower prevalence in many other cancers including pancreatic, colon, breast and salivary gland." (PMID 39655713, 2025).
thyroid tumor (7 papers, 2004 to 2025). A benign or malignant neoplasm affecting the thyroid gland. "In particular, the RET/PTC3 rearrangement, in which RET is fused to the promoter region of the NCOA4 gene (also known as ELE1), was described in a post-Chernobyl thyroid tumor." (PMID 33572167, 2021).
diabetes (6 papers, 2020 to 2025). "A high expression of NCOA4 induced the degradation of FTH1 and then promoted free iron release, which is a crucial element to cause ferroptosis, in diabetes myocardial ischemia reperfusion injury." (PMID 38069270, 2023). "Another study has found that inhibiting DNA methyltransferase 1 (DNMT-1) can alleviate ferroptosis through nuclear receptor coactivator 4 (NCOA4) mediated ferritinophagy during diabetes myocardial IRI." (PMID 38076182, 2023). "Whether DNMT-1 can affect ferroptosis through NCOA4 is worthy of further study in the process of diabetes myocardial IRI." (PMID 34588431, 2021). "Moreover, cryptochlorogenic acid (CCA) is an active compound in mulberry leaves, and CCA could inhibit ferroptosis by activating cystine/glutamate transporter (XC-)/GPX4/Nrf2 and inhibiting NCOA4 in diabetes, thereby reducing islet injury in the diabetic model." (PMID 38076182, 2023). "In diabetics, cryptoxaneic acid (CCA) activates the Xc-/GPX4/NRF2 pathway and inhibits nuclear receptor coactivator 4 (NCOA4), thereby inhibiting ferroptosis." (PMID 33424539, 2020). "Relative expression of HP (P < 0.01) A2M (P < 0.01), NCOA4 (P < 0.001) and HAMP (P < 0.01, P < 0.05) gene was significantly downregulated in PCOS female with complaint of kidney disease compared to PCOS females with diabetes, BP and both with diabetes and BP." (PMID 40057801, 2025). "In conclusion, inhibition of DNMT-1 could reduce ferroptosis during diabetes myocardial IRI and the NCOA4-mediated ferritinophagy may participate in the process." (PMID 34588431, 2021). "The purpose of this study was to investigate whether inhibition of DNA (cytosine-5)-methyltransferase 1 (DNMT-1) alleviated ferroptosis through nuclear receptor coactivator 4 (NCOA4)-mediated ferritinophagy during diabetes myocardial (DM) ischemia/reperfusion (I/R) injury (IRI)." (PMID 34588431, 2021).
hepatocellular carcinoma (6 papers, 2021 to 2026). A malignant tumor that arises from hepatocytes. "The results reveal that HYP can still elevate NCOA4 protein levels and enhance the ability of sorafenib to induce ferroptosis in hepatoma cells in vivo." (PMID 40514377, 2025). "A coumarin derivative extracted from a variety of plants, Esculetin (6,7-dihydroxycoumarin), was shown to induce ferritinophagy in hepatocellular carcinoma cells through the NCOA4/LC3II/FTH1 pathway, promoting ferroptosis and exerting anticancer effects." (PMID 38834843, 2024). "In addition, polypyrimidine pathway binding protein 1 (PTBP1) has been shown to mediate ferroptosis in hepatocellular carcinoma cells by regulating the translation of NCOA4, and the PTBP1-NCOA4 axis may be an important pathway for ferritinophagy-mediated ferroptosis." (PMID 38834843, 2024).
iron metabolism disorders (5 papers, 2022 to 2026). "In this study, iron overload resulted in iron accumulation and iron metabolism disorders and induced NCOA4-mediated ferritinophagy and ferroptosis." (PMID 36364817, 2022). "It is important to note here that although the role of NCOA4 in cellular and systemic iron mobilization is well studied in human cell lines and various mouse models, the role of NCOA4 in human iron disorders has not been well studied." (PMID 35888733, 2022).
non-alcoholic fatty liver disease (5 papers, 2021 to 2025). "Studies have demonstrated that curcumol can target YAP/NCOA4 to regulate ferritinophagy against hepatocyte senescence for the treatment of non-alcoholic fatty liver disease (NAFLD)." (PMID 38834843, 2024). "Conversely, reduced YAP levels promote the binding of NCOA4 to FTH1, intensifying hepatocyte ferroptosis in non-alcoholic fatty liver disease." (PMID 40374601, 2025). "In non-alcoholic fatty liver disease, curcumol inhibits hepatocyte senescence, iron overload and ferritinophagy through YAP/NCOA4 signaling." (PMID 38914581, 2024). "In non-alcoholic fatty liver disease, curcumol inhibits ferritinophagy to restrain hepatocyte senescence through the YAP/NCOA4 axis." (PMID 38001078, 2023).